KIAA1671 (KIAA1671)
Tractability: PROTAC: ubiquitination databases record sites on it; its protein half-life has been measured.
Gene: Protein-coding gene on chromosome 22 (24,952,711 to 25,197,448, forward strand). Ensembl gene ENSG00000197077.
Subcellular location (Human Protein Atlas): Microtubules; Primary cilium; Cytokinetic bridge
Gene Ontology:
Molecular function: protein binding
Cellular component: cilium
Genetic constraint (gnomAD): Loss-of-function variants: 51 observed, 122.71 expected, observed/expected ratio (o/e) 0.42, 90% interval 0.33 to 0.52. The upper end of that interval is the gene's LOEUF score, 0.52, which puts it in group 2 of 6, group 1 being the genes least tolerant of losing a copy. Missense variants: 2,296 observed, 2,326.1 expected, observed/expected ratio (o/e) 0.99, 90% interval 0.95 to 1.02. Synonymous variants: 966 observed, 949.33 expected, observed/expected ratio (o/e) 1.02, 90% interval 0.96 to 1.07.
Homologues: Orthologues: chimpanzee KIAA1671 (98% identical), macaque KIAA1671 (93% identical), dog KIAA1671 (68% identical), rabbit KIAA1671 (59% identical), mouse 2900026A02Rik (55% identical), rat Kiaa1671 (53% identical), tropical clawed frog KIAA1671 (26% identical), zebrafish si:ch73-138n13.1 (15% identical), guinea pig Kiaa1671 (14% identical), zebrafish tnks1bp1 (11% identical). Paralogues in human: CNOT12 (15% identical).
Diseases named in the same sentence as KIAA1671 in open-access papers:
KIAA1671 is named in the same sentence as 5 diseases in open-access papers, as found by Europe PMC text mining. Sharing a sentence is not in itself a finding about the gene and the disease.
KIAA1671 shares sentences with these, for which no sentence is quoted: breast carcinoma (1 paper); cancer (1); glioma (1); intraductal papillary mucinous neoplasms (1); papillary thyroid carcinoma (1).